ID4 (inhibitor of DNA binding 4)
Diseases named in the same sentence as ID4 in open-access papers (continued):
Sharing a sentence is not in itself a finding about the gene and the disease.
tumor (98 papers, 2005 to 2025). "An analysis of the resulting mutational signature established that ID4 substantially contributed in all tumours, accounting for 32% of acquired indels." (PMID 35140396, 2022). "In conclusion, our results support that ID1 and ID4 have a role as pro-oncogenes in BC and are associated with tumor aggressiveness in BC subtypes." (PMID 33514024, 2021). "On the contrary, other authors have reported that loss of ID4 by hypermethylation increases tumor progression and metastasis, supporting the theory of ID4 being a tumor suppressor gene." (PMID 33514024, 2021). "In the last decades, the role of ID4 as a tumor suppressor gene has been proposed based on evidence showing an increase in tumor progression and the risk of metastasis following the loss of ID4 by hypermethylation." (PMID 33514024, 2021). "the present study, we found that miR-335 was overexpressed in AML patients, and increased expression of miR-335 expression was negatively associated with decreased expression of ID4, which acted as tumor suppressor in AML." (PMID 31147526, 2019). "Consistent with our previous observation, in the present study loss of ID4 enhanced in vivo tumor growth in the castration‐resistant environment, more importantly through FKBP52‐mediated AR signaling pathway." (PMID 28252832, 2017). "In a majority of human cancers, ID4 acted as a tumour suppressor and was low‐expressed caused by its promoter hypermethylation." (PMID 28452111, 2017). "Overexpression of ID4 was also associated with basal-like tumours, in agreement with a recent report on ID4 protein overexpression in triple negative breast tumours (TNBC), and also detected in the vant’ Veer series." (PMID 23555842, 2013). "In this study we provide functional evidence that Id4 indeed acts as a tumor suppressor and is part of a cancer associated epigenetic re-programming." (PMID 19500415, 2009). "Tumor suppressor roles of Id4, based on its loss of expression in association with promoter hypermethylation have been suggested in leukemia, breast, colorectal and gastric cancers." (PMID 19500415, 2009). "Tumours with ID4 promoter methylation showed distinct loss of ID4 expression on both transcription and protein level." (PMID 18513385, 2008). "Interestingly, ID4 expression is higher in macrophages associated with invasive tumor cells compared to general TAMs, and ID4-correlated mRNAs are involved in various pathways that were previously reported as relevant for TAM functions." (PMID 32054109, 2020). "To evaluate the possible functional implication of the ID4 protein in macrophages, we searched for genes and pathways correlated with ID4 in a tumor-associated macrophage dataset as well as in the TCGA dataset, the latter being necessary to identify ID4-associated factors relevant for human cancer." (PMID 32054109, 2020). "The underlying ID4 dependent molecular mechanisms could therefore be exploited to develop therapeutic strategies to re-activate AR as a tumor suppressor." (PMID 27487149, 2016). "Loss of Id4 gene expression in many cancers in association with promoter hypermethylation has led to the proposal that Id4 may act as a tumor suppressor." (PMID 19500415, 2009). "Note, that in these tumour tissues nearly complete loss of ID4 protein expression was evident." (PMID 18513385, 2008). "ID4 is indeed a novel tumour suppressor gene in normal human breast tissue and is epigenetically silenced during cancer development, indicating increased risk for tumour relapse." (PMID 18513385, 2008). "In order to confirm that promoter methylation also affects loss of ID4 protein, we performed a parallel analysis of ID4 promoter methylation, mRNA and protein expression in three matched samples with normal breast tissue and corresponding tumour tissue." (PMID 18513385, 2008). "ID4 served as a tumor suppressor gene in GC and was required for H. pylori-mediated tumorigenic activities in vitro cellular and in vivo tumor-bearing mouse models." (PMID 41057303, 2025).
tumor (continued). "Our study provides new insights into the oncogenic roles of ID4 in tumor cell migration and YAP/TAZ pathway activation, suggesting VEGFA/ VEGFR2/ integrin β3 axis as a potential target for BC treatment." (PMID 38321003, 2024). "Here, we showed that ID4 protein expression in BC contributes to tumor aggressiveness stimulating cell migration and invasion by regulating VEGFA production." (PMID 38321003, 2024). "We found that siRNA-mediated suppression of ID4 in ELK3KD cells restored extravasation competence, and that stable shRNA-mediated suppression of ID4 in ELK3KD cells enabled the formation of a tumor mass in the lung." (PMID 38188675, 2023). "ID4 was the only gene whose expression was significantly lower in tumor tissue than in normal tissue (1085 tumor tissues vs. 291 normal tissues; analyzed by GEPIA2)." (PMID 38188675, 2023). "We observed a significantly higher expression of ID4 in tumor cell lines than the healthy breast epithelium cell line." (PMID 33514024, 2021). "Nevertheless, opposite data claiming an increased expression of ID4 in various tumor types have also been reported." (PMID 33514024, 2021). "The inhibitor of DNA binding 4 (ID4), a dominant negative helix-loop-helix protein, acts as a tumor suppressor gene." (PMID 34827720, 2021). "Our in vitro data demonstrates that the expression of ID4 is higher in tumor cell lines than in healthy breast epithelium." (PMID 33514024, 2021). "Id4 overexpression significantly reduced tumor growth and hepatic metastasis in the mice inoculated with HCT116-Id4 cells." (PMID 33936204, 2021). "Despite the structural similarity, Id4 still has different roles in the tumorigenesis, tumor invasion, and metastasis as compared to other Id family members." (PMID 33936204, 2021). "Increased expression of ID4 has been observed in some tumor types such as hepatocellular carcinoma, glioblastoma, or melanoma, indicating a possible role in tumor development." (PMID 33514024, 2021). "The Id4-/- mice represented a complex phenotype in which at least two major tumor suppressors Nkx3.1 and Pten were below detection by conventional immune-histochemistry." (PMID 33884281, 2021). "In the in vivo model, Id4 overexpression inhibited the tumor growth and metastasis in the nude mice." (PMID 33936204, 2021). "We observed that a large part of the macrophage population expresses the ID4 protein in the tumor stroma." (PMID 32054109, 2020). "In young-PD patients ERG/MYC/NEDD4L/MAOA oncogene panel was found to be activated whereas in old-PD patients HLA-A/B/ANXA2/LDHB/ID4 tumor suppressor panel was down regulated." (PMID 33575208, 2020). "The new member of this family, ID4, controls tumor progress of different cancers by regulating upstream of key developmental pathways 10-12." (PMID 32328189, 2020). "Western blot, TCGA database, Immunoprecipitation (IP), Chromatin Immunoprecipitation (ChIP) and Luciferase reporter assay were used to investigate the tumor promotion mechanisms of ID4." (PMID 32328189, 2020). "Other studies clarified that the ID4 gene expression in normal breast and stomach tissues is highly elevated in comparison to cancerous tissues denoting the tumor suppressive role for this protein." (PMID 30876429, 2019). "Although Id4 has also been shown to participate in tumor progression, its functional role remains ambiguous." (PMID 31847356, 2019). "Epigenetic silencing of ID4 (a characteristic mechanism to downregulate tumor suppressor genes during cancer progression) has been described in mammary columnar cell lesions, ductal carcinoma in situ, and invasive carcinomas." (PMID 30139383, 2018). "miR-107 and another miRNA of this family (miR-195) that we have found downregulated in an ID4-dependent manner in macrophages were previously shown to have tumour-suppressive properties in BC." (PMID 29921315, 2018).
tumor (continued). "Our observations that ectopic expression of ID4 also leads to a significant decrease in the number of colonies is also in line with a tumor suppressor role for this protein." (PMID 30139383, 2018). "In vivo the Id4-nanoparticle approach has been shown to be more efficient than the administration of docetaxel in reducing the tumor volume." (PMID 28122577, 2017). "Taken together, our study demonstrates that epigenetically silenced ID4 acts as a tumour suppressor in myeloid malignancies." (PMID 28452111, 2017). "Tumor growth and IHC studies clearly demonstrates that ID4 promotes sensitivity to DTX treatment by significantly promoting apoptosis and blocking cell proliferation." (PMID 27487149, 2016). "The major observation that needs to be further investigated is the ability of ID4 to revert the oncogenic AR in PCa back to normal AR activity which appears to be that of a tumor suppressor." (PMID 27487149, 2016). "We observed a flipped distribution of ID4 transcript compared to BRCA1 abundance in the two tumor classes." (PMID 27077368, 2016). "Functionally, the NC based delivery of recombinant ID4 is biologically active in terms of an anti-tumor activity and re-activation of tumor suppressor pathways that are relevant in PCa such as expression of PCa tumor suppressor NKX3.1." (PMID 27487149, 2016). "Inhibitor of DNA binding protein 4 (ID4) is a member of the dominant-negative basic helix-loop-helix transcription factor family that lacks DNA binding activity and has tumor suppressor function." (PMID 24810788, 2014). "In this dataset, positive TCF3, ID1 and ID4 expression were more frequent (Chi-square test, p = 0.033, p<0.001, and p<0.001, respectively) in the basal-like tumours." (PMID 23555842, 2013). "A multivariate Cox regression model (which considered age at diagnosis, gender, degree of tumor surgical resection, and ID4 expression status) showed that ID4 expression (hyper or hypoexpression) alone had no impact on patient’s prognosis." (PMID 23613880, 2013). "ID4 acts directly as tumor suppressor by influencing cellular processes at multiple levels that lead to a decreased cell proliferation." (PMID 23285167, 2012). "Collectively, the data from our laboratory demonstrated that Id4 acts as a potential tumor suppressor but its expression in prostate tissue is at best conflicting." (PMID 23342267, 2012). "The tumor-promoting properties of Id1, Id2, and Id3 are at least partially shared by Id4 also: Id4 has been shown to promote neoplastic transformation/growth." (PMID 23342267, 2012). "On the contrary, epigenetic silencing of Id4 in many cancers tends to support its role as a tumor suppressor." (PMID 23342267, 2012). "Contrary to these observations, studies have also demonstrated pro-tumor function of Id4 that is consistent with its other family members Id1, Id2, and Id3." (PMID 23342267, 2012). "Our results, in general agree with the majority of results that support the role of Id4 as a tumor suppressor due to epigenetic inactivation in other cancers." (PMID 23342267, 2012). "Id4 protein nuclear staining in carcinomas was also positively correlated with proliferation, invasiveness and tumor weight." (PMID 21293053, 2010). "Recent studies revealed that the ID4 gene can be silenced through promoter hypermethylation in various tumors, suggesting a tumor suppressive role." (PMID 20070914, 2010). "In proliferating cells Id4 plays a role in the recruitment of new blood vessels, thereby ensuring the survival and the spreading of tumor cells." (PMID 21293053, 2010).
tumor (continued). "Collectively, our results suggest that Id4 acts as a potential tumor suppressor, possibly through multiple pathways." (PMID 19500415, 2009). "In accordance with the mRNA data, the abundance of ID4 protein in the tumour was very similar to that found in the corresponding normal tissue (N)." (PMID 18513385, 2008). "Genes encoding proteins involved in ion and electron transport (CYB5R2, GABRP), and genes encoding proteins with transcription factor and regulator activity (ELF5, ID4) were downregulated in both populations of tumor cells." (PMID 17389037, 2007). "ID4 is frequently silenced by promoter hypermethylation in FL66, suggesting a tumor-suppressive role whose loss could facilitate disease progression." (PMID 41238550, 2025). "ID4 operates as a prodifferentiation factor and serves as a tumor suppressor in most cancer cells." (PMID 38188675, 2023). "Previous research has reported that ID4 acts as a tumor suppressor in CRC progression." (PMID 35656024, 2022). "Collectively, these findings implicate that Id4 may serve as a tumor suppressor and has the promise to become a target in the clinical treatments of CRC." (PMID 33936204, 2021). "ID4 methylation is correlated with histopathological tumor grade and poor prognosis." (PMID 34827720, 2021). "Regarding ID4, all tumor cell lines showed increased expression compared with 184A1 (all p ≤ 0.06), meaning that this gene could have a specific role in BC pathogenesis." (PMID 33514024, 2021). "As a tumor suppressor, ID4 could promote the proliferation and inhibit the apoptosis of tumor cells in prostate, lung, and gastric cancers." (PMID 32368784, 2020). "In addition, it was also found that the expression level of ID4 was significantly different in various tumor stages." (PMID 32003423, 2020). "The function of ID4 in different tumor types remains controversial." (PMID 33488950, 2020). "However, in breast cancer, Id4 has been determined to be an oncogene, which promotes tumor neo-angiogenesis by the regulation of IL-8 and Gro-α." (PMID 31847356, 2019). "Our data also showed that high ID4 mRNA expression level is associated with reduced distant metastasis-free survival (DMFS) and overall survival (OS), specifically in patients carrying tumours highly infiltrated by macrophages." (PMID 29921315, 2018). "Interestingly, ID4 messenger RNA (mRNA) levels robustly predicted survival, specifically in the subset of tumours showing high macrophage infiltration." (PMID 29921315, 2018). "Therefore, there are different expression levels of ID4 between these tumor types and possibly different pathways are turned on or off according to differences in ID4 expression." (PMID 30139383, 2018). "Here, we hypothesize that ID4 behaves as both, but its role in breast differs according to the estrogen receptor (ER) status of the tumor." (PMID 30139383, 2018). "Given that high ID4 expression was only beneficial in the ER+ group, we speculate that ID4 has a tumor suppressor role in these tumors." (PMID 30139383, 2018). "We also found that the expression of Id4 protein was up-regulated in HCC patient tumor samples." (PMID 28143562, 2017). "In contrast, lack of this regulation in androgen-independent cancers might lead to cell proliferation (Id1 and Id3 up-regulation), cell survival (Id2 down-regulation) and decreased tumor suppression (Id4 down-regulation)." (PMID 28122577, 2017). "It has been proposed that in androgen-dependent prostate cancers androgen might regulate proliferation, apoptosis and tumor suppression via Id1/Id3, Id2 and Id4 regulation, respectively." (PMID 28122577, 2017). "We found that the expression of Id4 protein was up-regulated in tumor tissues from HCC patients." (PMID 28143562, 2017).
tumor (continued). "In addition, ID4 acted as a tumor suppressor in AML and epigenetic dysregulation of ID4 independently affected clinical outcome in patients with AML." (PMID 29190891, 2017). "On the contrary, other studies showed that Id4 has a tumor-suppressive effect." (PMID 28143562, 2017). "Mechanistically, how ID4 promotes multiple tumor suppressive pathways including sensitivity to chemotherapeutic agents is largely unknown." (PMID 27487149, 2016). "ID4 may regulate a specific or combination of these pathways that may ultimately decide whether AR acts as a tumor suppressor or an oncogene." (PMID 27487149, 2016). "The exclusion of promoter methylation analysis from this study was due to the fact that in the cases with hypermethylation (almost exclusively TNBCs) the BRCA1:ID4 ratio and protein presence and localization were able to classify the tumor into the appropriate BRCA1 category." (PMID 27077368, 2016). "Consequently, re-constituting ID4 protein expression through ID4NC in L(-)ID4 reverses these effects suggesting specificity of ID4 tumor suppressor pathways such as increase in CDKNIs p27 and p21) and increased apoptosis following ID4NC treatment." (PMID 27487149, 2016). "The data strongly support the role of Id4 as a tumor suppressor." (PMID 23342267, 2012). "Paradoxically, Id4 appears to demonstrate both pro-tumor and anti-tumor properties." (PMID 23342267, 2012). "Although all these mechanisms are largely tumor-promoting, similar tumor-suppressive interactions that are unique to Id4 could exist that remains to be investigated." (PMID 23342267, 2012). "Perhaps, one of the mechanism by which AR becomes oncogenic could be due to its inability to trans-activate tumor suppressors such as Id4 due to promoter hypermethylation." (PMID 23342267, 2012). "We speculate that these opposing roles of Id4 sometimes in the cancers originating from the same tissue could be due to specific Id4 interactions that are pro- or anti-tumor." (PMID 23342267, 2012). "Evidence suggests that Id4 may share some functions with its family members but emerging data support the role of Id4 as a tumor-suppressive." (PMID 23342267, 2012). "We hypothesize that Id4 displays tumor suppressor functions in ER+ breast tumors where it is frequently inactivated by promoter hypermethylation." (PMID 21293053, 2010). "Following these findings a tumor suppressor role for Id4 in human breast has been proposed." (PMID 21293053, 2010). "The pro-tumor effect of Id4 is observed in bladder and rat mammary gland carcinomas." (PMID 19500415, 2009). "The results suggest that Id4 acts directly as a tumor suppressor by influencing a hierarchy of cellular processes at multiple levels that leads to a decreased cell proliferation and change in morphology that is possibly mediated through induction of previously silenced tumor suppressors." (PMID 19500415, 2009). "Both tumor promoting and tumor suppressor roles of Id4 have been reported in many cancers." (PMID 19500415, 2009). "The tumor suppressor role of Id4 appears to be unique as compared to other members of the Id gene family (Id1, Id2 and Id3) that may act as oncogenes or co-operating oncogenes in many cancers." (PMID 19500415, 2009). "The data strongly supports the role of Id4 as a putative tumor suppressor that may act as a regulatory gene by redirecting cell growth and differentiation." (PMID 19500415, 2009). "In this report we demonstrate that Id4 acts as a putative tumor suppressor." (PMID 19500415, 2009). "In contrast to the common ID4 downregulation in several human tumour entities, one study detected increased ID4 expression in rat mammary gland cells in conjunction with increased weight, proliferation and invasiveness of these tumours." (PMID 18513385, 2008).